STAT5A (signal transducer and activator of transcription 5A)
Diseases named in the same sentence as STAT5A in open-access papers (continued):
Sharing a sentence is not in itself a finding about the gene and the disease.
clear cell carcinomas (1 paper, 2008). "Surprisingly, secretory carcinomas of the breast maintain STAT5a expression, differing from other potential mimics such as apocrine metaplasia and mucinous or clear cell carcinomas, none of which expressed STAT5a in this study." (PMID 21655368, 2008).
complication (1 paper, 2024). Any disease or disorder that occurs during the course of, or because of, another disease, treatment, or procedure. "Our findings suggest that ZIPK plays a critical role in high glucose-induced vascular injury via STAT5A-mediated pathways, proposing that ZIPK is a potential therapeutic target for diabetic vascular complications." (PMID 39030705, 2024). "Our findings show that ZIPK plays a critical role in high glucose-induced vascular injury via STAT5A-mediated pathways, proposing that ZIPK is a potential therapeutic target for diabetic vascular complications." (PMID 39030705, 2024).
cyst (1 paper, 2023). A sac-like closed membranous structure that may be empty or contain fluid or amorphous material. "In addition, the data suggest that other targets of ROP16 (e.g., STAT5a) also play a role in cyst formation." (PMID 37068104, 2023).
depression (1 paper, 2018). "Hence, we speculated that the Stat5a may be associated with depression, and downregulation can lead to depressive-like behavior." (PMID 30194287, 2018). "Taken together, these findings may provide a further insight into the pathogenesis of depression, and suggest that the Stat5a gene is an important gene in depression." (PMID 30194287, 2018). "However, Stat5a (FC = 0.84) was downregulated in “depression microbiota” recipient mice compared with “healthy microbiota” recipient mice (p value < 0.01, FDR < 0.1)." (PMID 30194287, 2018).
diabetes (1 paper, 2025). "For hsa-miR-548k, main targets involved in diabetes-related pathways were identified, including TGFBR1, STAT1, NFKB1, MAPK1, and STAT5A." (PMID 40788916, 2025).
diabetic cardiomyopathy (1 paper, 2024). Diabetic cardiomyopathy is a disorder of the heart muscle in people with diabetes. "Through exploration of the transcription factors, we identified Tcf21, Arnt, Stat5a, and Stat5b as potentially key players in the development of diabetic cardiomyopathy, particularly in regulating endothelial cells and myocardial cells." (PMID 38664790, 2024).
diffuse astrocytoma (1 paper, 2021). A low-grade (WHO grade II) astrocytic neoplasm. "However, high levels of STAT5A were detected in 28.6%, 18.2%, and 22.2% of the GBM samples, diffuse astrocytoma samples, and normal cortex samples, respectively." (PMID 34276757, 2021).
hyperprolactinemia (1 paper, 2020). Abnormally high level of prolactin in the blood. "Most recently, a role of STAT5a signaling in pre-cancerous breast lesions was also reported, where hyperprolactinemia-inducing antipsychotics were demonstrated to induce activation of STAT5a and suppress apoptosis." (PMID 32633727, 2020).
Hypertension (1 paper, 2024). The presence of chronic increased pressure in the systemic arterial system. "STAT5A also regulates endothelial function and its downregulation may reduce the ability of blood vessels to dilate thereby creating internal pressure that may result to hypertension." (PMID 38895458, 2024). "Additionally, downregulation of STAT5A gene may lead to excessive smooth muscle proliferation, ultimately resulting in vascular remodeling and increased vascular resistance that contributes to hypertension." (PMID 38895458, 2024).
interstitial cystitis (1 paper, 2024). A rare chronic debilitating urogenital disease characterized by urinary frequency, urgency, and pelvic pain. "Seven hub genes (SPTBN1, PSME4, CHAC2, ERLEC1, ASB3, STAT5A, and STAT3) were identified as differentially expressed between interstitial cystitis patients and healthy individuals, representing potential therapeutic targets." (PMID 39399486, 2024).
ischemic heart disease (1 paper, 2025). "STAT5A has been previously implicated in ischemic heart disease, making it a compelling candidate for further investigation." (PMID 40564023, 2025).
leprosy (1 paper, 2014). Leprosy is a chronic infectious disease affecting primarily the skin and peripheral nervous system. "Therefore, we next investigated the status of STAT5A for TGF-β production in PBMC of 3 subjects each of both leprosy types using flowcytometry analysis." (PMID 24454972, 2014).
lymphoblastic lymphoma (1 paper, 2018). A lymphoma composed of immature small to medium-sized precursor lymphoid cells (lymphoblasts). "Transgenic mouse models expressing high levels of murine Stat5a or Stat5b developed lymphoblastic lymphoma at low penetrance (5%–25%) and with a late onset (up to 456 days)." (PMID 29200404, 2018).
memory (1 paper, 2021). The activities involved in the mental information processing system that receives (registers), modifies, stores, and retrieves informational stimuli. "Interestingly, brain-specific Stat5a/Stat5b knockout mice exhibit memory deficits, suggesting that STAT5 is a downstream signaling pathway potentially recruited by GHR to modulate memory." (PMID 33440789, 2021).
microcytic anemia (1 paper, 2019). Anemia in which the red blood cell volume is decreased. "The complete genetic abrogation of STAT5A and STAT5B (Stat5a/b−/−) resulted in perinatal lethality; the few survivors displayed severe microcytic anemia, reduced numbers of CD8+ T cells, and a block in the pre–pro-B cell stage." (PMID 31690038, 2019).
Myocardial fibrosis (1 paper, 2025). "Histological assessment demonstrated that STAT5A overexpression attenuated myocardial fibrosis and collagen deposition in both the border and remote zones of the infarcted heart." (PMID 40564023, 2025).
oral cancer (1 paper, 2015). "Among the 4 hub genes, the three genes EGFR, PDGFRB, STAT5A have already been annotated to be related to oral cancer according to GeneCards." (PMID 26064958, 2015).
ovarian serous cystadenocarcinoma (1 paper, 2022). A malignant serous cystic epithelial neoplasm arising from the ovary. "STAT5A was altered (73%) in 272 samples from 374 patients with ovarian serous cystadenocarcinoma." (PMID 36524006, 2022). "Besides, STAT5A was negatively related to tumor-promoting MMP2 expression in human ovarian serous cystadenocarcinoma cell line HO8910." (PMID 36524006, 2022).
parasite infections (1 paper, 2025). "Our GO enrichment analysis shows that response to stimulus is the most significantly enriched biological process, which is highly consistent with host immune response mechanisms triggered by parasite infections, in which the core genes TNF, STAT3, STAT5A, PDGFB, ADRB2 and SMO were included." (PMID 41153368, 2025).
Parkinson disease (1 paper, 2022). A progressive degenerative disorder of the central nervous system characterized by loss of dopamine producing neurons in the substantia nigra and the presence of Lewy bodies in the substantia nigra and locus coeruleus. "CRISPR-Cas9-mediated STAT5A/B deletions were induced in a neuroblastoma cell line to determine the correlation of neuroprotective activity with the IFN-β/STAT5 pathway in neurodegenerative diseases such as Parkinson’s disease." (PMID 36232600, 2022).
penile cancer (1 paper, 2024). A primary or metastatic malignant neoplasm that affects the penis. "During malignant progression phase of penile cancer, the expression evolution of JAK-STAT-SOCS1 axis was characterized by the upregulation of JAK1, JAK3, STAT4, STAT5A and STAT6." (PMID 38774752, 2024). "There was a noticeable difference in the expression of JAK3, STAT4 and STAT5A between primary penile cancer and their metastatic lymph nodes." (PMID 38774752, 2024).
peripheral T-cell lymphoma (1 paper, 2021). "High activity levels of STAT5A and STAT5B variants in the hematopoietic system of transgenic mice can lead to a lethal condition resembling human peripheral T-cell lymphoma (PTCL) and elevated expression of STAT5A/B has been detected in human PTCL samples." (PMID 34055801, 2021).
renal carcinoma (1 paper, 2021). A carcinoma arising from the epithelium of the renal parenchyma or the renal pelvis. "Together, these findings confirmed the relationship of PTP4A3 to immune cell infiltration and CD79A, CSF1R, INOS, COX2, STAT5A, FOXP3 and CCR8 in KIRP, suggesting an important immune regulation role of PTP4A3 in the renal cancer microenvironment." (PMID 34630392, 2021).
retinoblastoma (1 paper, 2022). A malignant tumor that originates in the nuclear layer of the retina.
sarcoidosis (1 paper, 2025). Sarcoidosis is a multisystemic disorder of unknown cause characterized by the formation of immune granulomas in involved organs. "A heatmap analysis further demonstrated an upregulation of key genes involved in these pathways, particularly in the progressive sarcoidosis group, including CSF2RB, CSF2RA, IL3RA, STAT5A, and STAT1." (PMID 41476976, 2025).
sarcoma (1 paper, 2018). A usually aggressive malignant neoplasm of the soft tissue or bone. "In our DFSP patients, EGFR and STAT5a/b phosphorylation levels were correlated, suggesting that a similar STAT-mediated EGFR signaling could be involved DFSP evolution to high grade sarcoma." (PMID 29492209, 2018). "We thus demonstrated that in DFSP evolution to high grade sarcoma, EGFR and SNAIL were involved, with EGFR activation and signaling through TOR and STAT5a/b downstream effectors, which could lead on to new therapies for advanced DFSP." (PMID 29492209, 2018).
Sepsis (1 paper, 2025). Sepsis is defined as life-threatening organ dysfunction caused by a dysregulated host response to infection. "Interestingly, the expression of Inhba, Smad3, Acvr1b, Acvr2a, Stat5a, and Stat5b was all higher in the macrophages of patients compared with healthy volunteers, suggesting that the activin A/Smad3/STAT5 axis is also involved in human sepsis." (PMID 40067393, 2025).
skin cancer (1 paper, 2023). "High STAT5a expression in skin cancer also seemed to be associated with higher survival." (PMID 37369132, 2023). "We found that bladder, breast, and skin cancer patients with high STAT5a expression had favorable overall survival compared to patients with low STAT5a expression." (PMID 37369132, 2023).
squamous cell carcinoma (1 paper, 2024). A carcinoma arising from squamous epithelial cells. "The discovery that hypermethylated STAT5A leads to regulatory suppression and immune cell depletion in squamous cell carcinomas underscores the significance of STAT5A's epigenetic regulation in immunosuppression." (PMID 39525954, 2024).
Stroke (1 paper, 2024). Sudden impairment of blood flow to a part of the brain due to occlusion or rupture of an artery to the brain. "Notably, increased activity for multiple of these TFs (e.g. Stat5a, Stat3, Myc, Hif1a, Snai1) was also observed in stroke-specific OPC and Oligodendrocyte subsets." (PMID 39043661, 2024).
type 2 diabetic (1 paper, 2018). "It was found that the expression of STAT5A and SREBP1c in subcutaneous adipose tissue was significantly reduced in type 2 diabetic patients." (PMID 29977307, 2018). "In turn, STAT5A was shown to be involved in adipocyte differentiation probably by controlling the expression of PPARγ, and type 2 diabetic patients had decreased expression of both PPARγ and STAT5A genes." (PMID 29977307, 2018).
vitamin D deficiency (1 paper, 2024). A nutritional condition produced by a deficiency of VITAMIN D in the diet, insufficient production of vitamin D in the skin, inadequate absorption of vitamin D from the diet, or abnormal conversion of vitamin D to its bioactive metabolites. "Expression of the Chr17q21.2 genes Stat3, Stat5a, and Stat5b was not affected by vitamin D deficiency." (PMID 38567749, 2024).
tumor (142 papers, 2008 to 2026). "Previous studies have reported that various tumor-associated genes are regulated by STAT5A/STAT5B, which maintain multiple cancer-related pathways." (PMID 41048344, 2025). "These structural distinctions likely underpin the divergent biological behaviors observed: STAT5B exhibits predominantly tumor-suppressive associations across epithelial cancers, while STAT5A demonstrates dual or even opposing effects in certain malignancies." (PMID 41301421, 2025). "In current study, STAT5A was predicted to be positively associated with tumor-infiltrating immune cells, including B/T cells, macrophages and dendritic cells." (PMID 38124049, 2023). "Two adjacent genes encoded STAT5 in mammals, namely, Stat5a and Stat5b, which drive tumor development, metastasis, survival and drug resistance to treatment, NK cell development, maturation, survival, and cytotoxicity." (PMID 36324680, 2022). "Next, we set out to elaborate the mechanisms of how loss of STAT5A expression promoted glucose metabolism and tumor growth in HCC." (PMID 33155364, 2021). "Conversely, transgenic overexpression of a constitutively activated STAT5a mutant or its upstream JAK2 activator was sufficient to cause tumor formation in the mammary glands of mice." (PMID 32633727, 2020). "In CWR22Rv xenografts, adenovirus-mediated overexpression of a dominant-negative STAT5A/B variant was shown to reduce tumor incidence, indicating a reduction in stem-like properties following STAT5 inhibition." (PMID 31269779, 2019). "We verified the involvement of T-cell receptor signaling pathways in HNSCC as well as associated oncogenes such as LCK and PLCB1, and tumor suppressors such as STAT5A, PTPN6, PARK2." (PMID 21884569, 2011). "Howerer, loss of STAT5A are associated with tumor progression and unfavorable clinical outcomes, meaning that drugs targeting STAT5A may caused unexpected outcomes." (PMID 38124049, 2023). "Importantly, STAT5A-V706fs mutation tumor cells exhibited increased activation of STAT5A pathway and PD-L1 overexpression in the presence of GM-CSF." (PMID 34051805, 2021). "Thus, an association between high kinase activity mediated by STAT5A and development of CR disease was uncovered both in xenografts and patient tumor samples." (PMID 23675504, 2013). "Molecular mechanistic studies in vivo will be needed to determine whether causal mechanisms exist by which Stat5a affects tumor responsiveness to antiestrogen therapy." (PMID 23036105, 2012). "Stat5 activation initiates cell differentiation through expression of the CDH-1-β-catenin complex, which may suggest a protective effect of PRL against neoplasm formation, because decreased Stat5a activation was associated with metastatic progression in human breast cancer." (PMID 26370564, 2015). "In cases where HIF1A is expressed, there was an upregulation of JAK2 and STAT5A proteins in tumor tissue, alongside EPOR." (PMID 40332447, 2025). "The highly homologous transcription factors STAT5a and STAT5b are overactivated in many human tumor types." (PMID 41320753, 2025). "Phenotypic characterization and tumor‐killing capacity between Stat5a‐overexpressing T cells with control groups were performed." (PMID 40936164, 2025). "While STAT5A has been characterized as a context-dependent modulator of tumor progression, the prognostic significance of STAT5B remains less clear." (PMID 41301421, 2025). "This contrasts with STAT5A, which displays more variable expression patterns and can act as either oncogenic or tumor-suppressive depending on cellular and molecular context." (PMID 41301421, 2025). "Specifically, CD3+CD4+ splenocytes from aged OVX 4T1 tumor-bearing mice treated with calcitriol showed increased Stat5a and Vdr mRNA expression." (PMID 40894304, 2025). "In turn, intratumoral infiltrating lymphocytes secrete IL-2 to activate tumor STAT5A signaling, which further synergizes with TET2 to epigenetically upregulate tumor cGAS, indicating a positive feedback loop." (PMID 38177099, 2024).
tumor (continued). "KLF4 functions as a tumor suppressor and its transcriptional activity is repressed by the binding of STAT5A to its promoter." (PMID 38879589, 2024). "In contrast, Tet2 overexpression in combination with IL-2 stimulation led to more increase in Cgas expression than either alone, suggesting that TET2 synergizes with STAT5A signaling to promote tumor cGAS expression." (PMID 38177099, 2024). "We validated this approach by creating a new line of STAT5A-iPSCs which can be differentiated to STAT5A-expressing macrophages with both NK cell and macrophage features such as perforin production, phagocytosis, and anti-tumor functions." (PMID 39872864, 2024). "Activation of STAT1, STAT2, STAT3, STAT4, and STAT6 was observed in expanded bile duct epithelium and tumor cells, while expression of STAT5a and STAT5b was found in macrophages and connective tissues surrounding the tumor." (PMID 39290697, 2024). "To further characterize the oncogenic role of STAT5A in GC, we conducted a subcutaneous tumor formation experiment in nude mice to assess the impact of STAT5A knockdown on the tumorigenesis ability of GC cells in vivo." (PMID 38879589, 2024). "Mechanistically, TET2 mediated IL-2/STAT5A signaling epigenetically upregulates tumor cGAS expression and produces cGAMP." (PMID 38177099, 2024). "Unphosphorylated STAT5A helps to stabilize the heterochromatin upon binding to heterochromatin protein 1α(HP1α) and acts as a tumor suppressor." (PMID 39136000, 2024). "We have uncovered a new paradigm, which is that the primary tumor responsive to this therapy lost c-MYC-STAT5A/5B-PD-L1 interaction upon the treatment, and resistance is driven by STAT5A/5B." (PMID 39123391, 2024). "In general, it was displayed that higher expression of STAT1, STAT2, STAT3, STAT4, and STAT5A indicated a lower tumor purity." (PMID 36968603, 2023). "Dual inhibition of the transcription factors STAT5a and STAT5b is a valuable approach with promising applications in tumor biology." (PMID 36300584, 2023). "As the main step for tumor metastasis, colony formation was also negatively related to the STAT5A expression level." (PMID 38124049, 2023). "To investigate the role of STAT5a in cancers, we compared transcription levels of STAT5a in tumor tissues to normal tissues." (PMID 37369132, 2023). "Studies have also found that STAT5A has been involved in tumor progression through the intermediation transition of epithelial-mesenchymal." (PMID 35517418, 2022). "While all STATs interact with a larger number of oncogenes than tumour suppressors, the ratio of oncogenes to tumour suppressors is highest for STAT5A and STAT5B." (PMID 35229974, 2022). "The expression of STAT5A was positively associated with PCPG, while STAT5A expression was negatively related to all other tumor types." (PMID 36176415, 2022). "Ectopic expression of STAT5A enables the expansion of tumor‐specific CD4+ T cells and triggers antitumor CD8+ T‐cell responses." (PMID 35244291, 2022). "For instance, the hypoxia induced signal transducer and activator 5A (STAT5A) was proven to promote tumor cells growth by interrupting the activity of pyruvate dehydrogenase complex, a gatekeeper enzyme connecting glycolysis and the OXPHOS pathways." (PMID 36061190, 2022). "In vivo xenograft tumor assays showed STAT5A KO led to a profound reduction of in vivo tumor growth, which was partially compensated by mito-STAT5A reintroduction." (PMID 34148062, 2021). "Under hypoxia, the translocation of STAT5A to mitochondria was increased to further strengthen the Warburg effect and support in vitro cell growth and in vivo tumor growth." (PMID 34148062, 2021). "We suggest further studies are warranted to explore and develop inhibitors targeting STAT5A for tumor suppression." (PMID 34148062, 2021). "Visual scoring of STAT5a S726 phosphorylation revealed a significant increase in nuclear intensity in tumor samples grade III compared to grade I (nuclear Allred scores of 6 and 2, respectively)." (PMID 34188118, 2021).